GLP1R (glucagon like peptide 1 receptor)
Diseases named in the same sentence as GLP1R in open-access papers (continued):
Sharing a sentence is not in itself a finding about the gene and the disease.
type 2 diabetes (continued). "Two types of fixed-ratio combinations of basal insulin and a glucagon-like peptide-1 receptor agonist (GLP-1RA) have been approved for use in type 2 diabetes." (PMID 36726134, 2023). "A prototypical example is glucagon-like peptide-1 receptor (GLP-1R), which predominately couples to the Gs effector and serves as an important drug target for the treatment of type 2 diabetes." (PMID 36875468, 2023). "Tirzepatide, a once-weekly glucose-dependent insulinotropic polypeptide/ glucagon-like peptide-1 receptor agonist, is approved in the United States, Europe and Japan for the treatment of type 2 diabetes." (PMID 36964557, 2023). "The first oral form of the glucagon-like peptide-1 receptor agonist, oral semaglutide, has recently been launched and potently controls glycemia and body weight in subjects with type 2 diabetes." (PMID 37686797, 2023). "These incretin functions have led to the approval of GLP-1R agonists for the treatment of type II diabetes." (PMID 37063267, 2023). "Type 2 diabetes (T2D) patients treated with subcutaneous exenatide show that it exerts a protective GLP-1R-dependent effect on postprandial endothelial function, compared to placebo, suggesting direct action on the endothelium." (PMID 37401947, 2023). "Liraglutide, as the first long-acting GLP-1R agonist, is the best-selling drug for the treatment of type 2 diabetes mellitus or obesity." (PMID 36771035, 2023). "The DURATION-5 trial investigated the effects of once-weekly (ExQW) versus twice-daily (ExBID) glucagon-like peptide-1 receptor agonism for the treatment of patients with type 2 diabetes." (PMID 37445623, 2023). "Recent large clinical trials have demonstrated cardiovascular benefits of similar overall magnitude for sodium–glucose cotransporter-2 inhibitor (SGLT-2i) and glucagon-like peptide-1 receptor agonist (GLP-1RA) therapy in subjects with type 2 diabetes." (PMID 37381019, 2023). "Glucagon-like peptide-1 receptor agonists (GLP-1RAs) are a class of medications commonly used in the treatment of type 2 diabetes mellitus (T2DM)." (PMID 37298276, 2023). "An increasing number of studies have been exploring the application of glucagon-like peptide-1 receptor agonists (GLP-1 RAs) in patients with NASH/NAFLD, as type 2 diabetes and obesity are so highly associated with this disease." (PMID 37623872, 2023). "Glucagon-like peptide-1 receptor (GLP-1R) is a critical therapeutic target for type 2 diabetes mellitus (T2DM)." (PMID 36677809, 2023). "Polyethylene glycol loxenatide (PEG-Loxe) is a novel, once-weekly glucagon-like peptide 1 receptor agonist that is approved in doses of 0.1 mg and 0.2 mg for the treatment of type 2 diabetes mellitus (T2DM)." (PMID 36777344, 2023). "Liraglutide is an acylated GLP-1 analog, and its pharmacokinetic and pharmacodynamic properties as a GLP-1R agonist make it an important therapeutic option for many patients with type 2 diabetes." (PMID 38186650, 2023). "Sodium-glucose cotransporter-2 inhibitors (SGLT2is) and glucagon-like peptide-1 receptor agonists (GLP-1RAs) are both considered to be part of standard care in the management of glycemia in type 2 diabetes." (PMID 35852840, 2022). "Incretin-based therapies with glucagon-like peptide-1 receptor agonists (GLP-1RA) are already established in the treatment of type 2 diabetes (T2D)." (PMID 36313764, 2022). "We evaluated the clinical impact, in daily clinical practice, of sodium-glucose co-transporter-2 inhibitors (SGLT2i) and glucagon-like peptide-1 receptor agonists (GLP1RA) therapies in patients with type 2 diabetes." (PMID 35859794, 2022). "Our approach is illustrated with a comparative cardiovascular safety study of glucagon-like peptide-1 receptor agonist (GLP-1ra) versus sulfonylurea (SU) in type 2 diabetes patients using Taiwan’s National Health Insurance Research Database 2003–2015." (PMID 34997053, 2022).
type 2 diabetes (continued). "The first agents targeting GLP-1 receptor (GLP-1R) signaling were developed to optimize the treatment of type 2 diabetes mellitus (T2D) as an adjunct to metformin when therapeutic goals where not met." (PMID 35264926, 2022). "These physiological properties have contributed towards the approval of GLP-1 receptor (GLP-1R) agonists for treatment of diabetes type 2 and obesity." (PMID 36229445, 2022). "As a result, the GLP-1 receptor (GLP-1R) has become an attractive target in the treatment of type 2 diabetes mellitus (T2DM)." (PMID 35745639, 2022). "Glucagon-like peptide-1 receptor (GLP-1R) agonists, commonly used in Type 2 diabetes mellitus treatment, have recently been considered potential candidates for PD treatment." (PMID 35681426, 2022). "Peptidicagonists of the glucagon-like peptide-1 receptor (GLP-1R)have gained a prominent role in the therapy of type-2 diabetes andare being considered for reducing food intake in obesity." (PMID 35349261, 2022). "Glucagon-like peptide-1 receptor agonists (GLP-1 RA) were originally approved for the treatment of type 2 diabetes by enhancement of glucose-stimulated insulin secretion." (PMID 36354682, 2022). "Glucagon-like peptide-1 receptor agonists (GLP-1 RAs) are broadly regarded as effective drugs in the treatment of type 2 diabetes mellitus (T2DM)." (PMID 35370875, 2022). "Activation of the GLP-1R lowers blood glucose in persons with type 2 diabetes while the GIPR is much less effective for this." (PMID 36050763, 2022). "Combined with the fact that semaglutide already has approval for use in Type 2 diabetes mellitus and a good safety record, there is potential for semaglutide and other GLP-1R agonists to be repurposed as neuroprotective therapeutic agents." (PMID 35970890, 2022). "Exenatide is a glucagon-like peptide-1 receptor (GLP1R) agonist, widely used as a medication to treat diabetes mellitus type 2." (PMID 35528523, 2022). "Glucagon-like peptide-1 receptor agonists (GLP-1RAs) provide substantial reductions in HbA1c and significant body weight loss in patients with type 2 diabetes (T2D) and obesity." (PMID 35184645, 2022). "In patients with type 2 diabetes, interventions that slow gastric emptying, e.g. glucagon-like peptide-1 receptor agonists, reduce postprandial blood glucose." (PMID 36194250, 2022). "Glucagon-like peptide-1 receptor agonists (GLP-1RA) are a group of important medications for patients with type 2 diabetes mellitus (T2DM)." (PMID 36386208, 2022). "Agonists of the glucagon-like peptide-1 receptor (GLP-1R), currently approved to treat type 2 diabetes, hold promise to improve steatosis and even steatohepatitis." (PMID 35140289, 2022). "Glucagon-like peptide-1 receptor agonists (GLP-1 RAs) are approved to treat type 2 diabetes mellitus." (PMID 36457601, 2022). "Glucagon-like peptide-1 (GLP-1) mimetics and GLP-1 receptor (GLP-1r) agonists are widely used drugs for glycemic control in type 2 diabetes." (PMID 35053423, 2022). "Combining a glucagon-like peptide-1 receptor agonist (GLP1-RA) with basal insulin is an emerging option when initiating injectable therapy in longstanding type 2 diabetes (T2DM)." (PMID 36244997, 2022). "Sodium-glucose cotransporter-2 inhibitors (SGLT2i) and glucagon-like peptide-1 receptor agonists (GLP-1RA) are recently introduced drug classes for the treatment of type 2 diabetes (T2D)." (PMID 35600575, 2022). "GLP1 receptor (GLP-1R) agonists are licensed for treating type 2 diabetes mellitus but have also demonstrated neuroprotective properties in a clinical trial for Parkinson’s disease." (PMID 35970890, 2022). "GLP-1 receptor (GLP-1R) agonists are effective drugs for the treatment of type 2 diabetes and obesity." (PMID 39872692, 2022). "Subcutaneous injection of a medication known as a glucagon-like peptide-1 receptor (GLP-1R) agonist has been used to treat type 2 diabetes." (PMID 36295527, 2022).
type 2 diabetes (continued). "Emerging evidence suggests that glucagon-like peptide-1 receptor (GLP-1R) agonists improve cardiovascular and renal outcomes in type 2 diabetes patients." (PMID 35884965, 2022). "Genetic variants of glucagon-like peptide-1 receptor (GLP-1R) have been reported to affect insulin secretion and susceptibility to type 2 diabetes." (PMID 36528605, 2022). "Glucagon-like peptide 1 receptor agonists (GLP-1 RAs) are a relatively new class of anti-diabetic medications that have exhibited very promising results in the treatment of type 2 diabetes mellitus (T2DM)." (PMID 35330453, 2022). "We evaluated time-course changes and the relationship between eating behavior and glycemic profile during the treatment of 34 obese type 2 diabetic patients with the glucagon-like peptide-1 receptor agonist (GLP1-RA) semaglutide." (PMID 35208221, 2022). "Glucagon-like peptide-1 receptor (GLP1R) agonists are used to treat type 2 diabetes (T2D), and polyagonists targeting multiple hormone receptors are investigated as potential therapeutics for T2D." (PMID 35750681, 2022). "GLP-1R activation was also found to ameliorate cognitive decline in Type 2 diabetes through metabolism-independent pathways." (PMID 36387940, 2022). "Glucagon-like peptide-1 receptor agonists (GLP-1RAs) are effective treatments for reducing hemoglobin A1c (HbA1c) in people with type 2 diabetes (T2D), including those with reduced kidney function." (PMID 36531884, 2022). "In type 2 diabetes, physicians have the opportunity to initiate cardioprotective glucose-lowering agents, such as glucagon-like peptide-1 receptor agonists or sodium-glucose cotransporter-2 inhibitors, after MI to reduce subsequent cardiovascular events." (PMID 36068573, 2022). "Here, we describe the discovery and characterization of BI 456906, a once-weekly, injectable GCGR/GLP-1R dual agonist currently in Phase II clinical development for obesity, type 2 diabetes, and NASH." (PMID 36356832, 2022). "The efficacy of glucagon-like peptide-1 receptor agonists in type 2 diabetes is well established, but their role in type 1 diabetes (T1DM) is less clear." (PMID 37908242, 2022). "This investigational agent has proven superior to selective GLP-1R agonists in clinical trials in subjects with type 2 diabetes mellitus." (PMID 35333651, 2022). "◊Sodium-glucose co-transporter 2 inhibitors, glucagon-like peptide-1 receptor agonists, incretin analogs are novel drugs approved for treating type-2 diabetes." (PMID 36518222, 2022). "Glucagon-like peptide-1 receptor agonists (GLP-1RAs) are considered as effective treatments for type 2 diabetes." (PMID 35184645, 2022). "Glucagon-like peptide-1 receptor (GLP-1R) agonists are promising agents for treating type 2 diabetes mellitus, since they augment glucose-dependent insulin secretion with minimized low risk of hypoglycaemia." (PMID 33995091, 2021). "These properties have made GLP-1R an important drug target in the field of type 2 diabetes and obesity." (PMID 33341919, 2021). "One of the potential compounds that regulate ATF4 expression is Exendin-4 (Exenatide), the first glucagon-like peptide 1 receptor agonist used clinically as a therapeutic agent for type 2 diabetes." (PMID 34547510, 2021). "Long acting peptides combining GCGR and GLP1R activity are in clinical trials for the treatment of type 2 diabetes and obesity." (PMID 33803183, 2021). "In a fed state, these effects are replicated by acute injection of the GLP-1R antagonist, exendin-9-39, especially in the type 2 diabetes group." (PMID 33803053, 2021). "Patients with type 2 diabetes treated with metformin and the GLP-1R agonist exenatide for 1 year display significantly reduced circulating TG, apoB48, and FFA following an early meal (50 g of fat, 75 g of carbohydrates, 35 g of protein)." (PMID 34660576, 2021). "This role of GLP-1R in controlling blood sugar levels has resulted in the approval of GLP-1R agonists for treatment of type 2 diabetes." (PMID 33902708, 2021).
type 2 diabetes (continued). "Glucagon-like peptide-1 receptor (GLP-1R) agonists are widely used in clinical practice as therapy for type 2 diabetes and obesity and one of its beneficial effects is that it induces a negative energy balance by decreasing appetite." (PMID 34066631, 2021). "GLP-1R agonists are widely prescribed for the treatment of type II diabetes and they also have the added benefit of suppressing appetite and producing weight loss." (PMID 35002645, 2021). "GLP-1R agonists have been successfully deployed for the treatment of type 2 diabetes, but it has been suggested that their efficacy is limited by target receptor desensitization and downregulation due to recruitment of β-arrestins." (PMID 33268378, 2021). "The binding of GLP-1R to its ligand (GLP-1) leads to the pancreatic β cells releasing glucose-dependent insulin; therefore, GLP-1R is a key target for the treatment of type 2 diabetes." (PMID 35011486, 2021). "Glucagon-like peptide-1 receptor (GLP-1R) agonist-based therapeutics for type 2 diabetes mellitus have attracted worldwide attention." (PMID 33995091, 2021). "Type 2 diabetes mellitus has recently been connected to PD, and anti-diabetic drugs, such as glucagon-like peptide-1 receptor agonists (GLP-1RAs), have been shown to possess neuroprotective effects in PD animal models." (PMID 34305527, 2021). "In recent years multiple novel therapies for the treatment and management of type 2 diabetes have emerged, among these are the glucagon like peptide-1 receptor agonists (GLP-1RA)." (PMID 34917038, 2021). "Glucagon-like peptide 1 receptor agonists (GLP1 RA) have been approved as a treatment option for type 2 diabetes." (PMID 34831417, 2021). "Glucagon‐like peptide‐1 receptor (GLP‐1R) agonists, such as exendin‐4 (Ex4), liraglutide and dulaglutide, regulate glucose homeostasis and are thus used to treat diabetes type II." (PMID 32770792, 2021). "Glucagon-like peptide-1 (GLP-1) increases insulin secretion from pancreatic beta-cells and GLP-1 receptor (GLP-1R) agonists are widely used as treatment for type 2 diabetes mellitus." (PMID 33903116, 2021). "With a high prevalence of obesity and non-alcoholic fatty liver disease among patients with type 2 diabetes mellitus, glucagon-like peptide-1 receptor agonist treatment shows promise in improving both diabetes and non-alcoholic fatty liver disease phenotype." (PMID 33897616, 2021). "Exendin-4 (Ex-4) is a GLP-1 receptor (GLP-1R) agonist clinically approved to treat patients with adult type 2 diabetes." (PMID 35002615, 2021). "Use of sodium-glucose transport protein 2 inhibitors (1.5 % type 1/8.7 % type 2 diabetes) and glucagon-like peptide-1 receptor agonists (0.6 % type 1/5.2 % type 2 diabetes) was limited." (PMID 34011313, 2021). "For instance, exendin-4 isolated from the Gila monster (Heloderma suspectum) is an example of a nature-derived peptide approved to treat diabetes mellitus type 2 by targeting glucagon-like peptide 1 receptor." (PMID 34744752, 2021). "Glucagon-like peptide-1 receptor agonists (GLP-1R) are employed in the treatment of type 2 diabetes but have recently been of interest in their potential to modify the progression of a range of neurological disorders including PD." (PMID 34830228, 2021). "Medline, Embase and Cochrane Central Register of Controlled Trials (CENTRAL) were searched for articles discussing the efficacy of glucagon-like peptide-1 receptor agonists on non-alcoholic fatty liver disease in patients with type 2 diabetes mellitus." (PMID 33897616, 2021). "Exenatide, a synthetic exendin-4, was the first GLP-1R agonist approved by the FDA in 2005 for the treatment of type 2 diabetes, as monotherapy or as add-on treatment to metformin and/or sulfonylurea where control was inadequate." (PMID 33925827, 2021).
type 2 diabetes (continued). "Lira is an approved antidiabetic drug that acts as an incretin mimetic GLP-1R agonist and is increasingly used to improve glycemic control, reduce the risk of heart attack, stroke, and cardiovascular death in adults with type 2 diabetes mellitus (T2DM)." (PMID 35002691, 2021). "Exenatide, a glucagon-like peptide-1 receptor agonist, is the active pharmaceutical ingredient in Byetta® and Bydureon®, two type 2 diabetes drug products that have generics and multiple follow-up formulations currently in development." (PMID 34452224, 2021). "SNPs around the exon region of the GLP1R gene were genotyped in a small sample of people with poorly controlled type 2 diabetes, who received exenatide for 3 days (5 μg twice daily) and were also treated with a continuous subcutaneous insulin infusion." (PMID 33594477, 2021). "In the current situation with increasing prevalence of obesity and type 2 diabetes globally, GLP-1 receptor (GLP-1R) agonists show remarkable therapeutic effects and attract attention." (PMID 34168616, 2021). "The glucagon-like peptide-1 (GLP-1) receptor is a key regulator of glucose homeostasis and a drug target for type 2 diabetes but available GLP-1R agonists are suboptimal due to several side-effects." (PMID 34145245, 2021). "Glucagon-like peptide-1 receptor agonists (GLP1-RA) are a wide class of hypoglycemic agents used in the treatment of type 2 diabetes." (PMID 34680477, 2021). "GLP-1R is a potent target for the treatment of type 2 diabetes mellitus, and small molecule agonists targeting GLP-1R can provide several potential benefits and overcome defects associated with peptide drugs." (PMID 33995091, 2021). "We investigated the effect of treatment with a glucagon-like peptide 1 receptor agonist (liraglutide) on oxidative stress measured as urinary nucleic acid oxidation in persons with type 2 diabetes." (PMID 34012064, 2021). "Exendin-4 (EX-4), a full agonist of glucagon-like peptide-1 receptor (GLP-1R), has been widely used in the clinical treatment of type 2 diabetes mellitus (T2DM)." (PMID 34532163, 2021). "Third, in recent years, some novel antidiabetic drugs such as sodium–glucose cotransporter-2 inhibitors and glucagon-like peptide-1 receptor agonists have been shown to provide cardiovascular and renal protection in patients with type 2 diabetes mellitus." (PMID 34439890, 2021). "This meta-analysis examined existing evidence on the efficacy of glucagon-like peptide-1 receptor agonists on the management of non-alcoholic fatty liver disease in patients with type 2 diabetes mellitus." (PMID 33897616, 2021). "Liraglutide is the second GLP-1R agonist to be licensed the FDA in 2010 for the treatment of type 2 diabetes." (PMID 33925827, 2021). "Glucagon-like peptide-1 receptor (GLP-1R) agonists are well established as an effective medication showing promising anti-diabetic effects in both animal models and patients with type 2 diabetes." (PMID 33925827, 2021). "Glucagon-like peptide-1 and glucagon receptor (GLP-1R/GCGR) co-agonism can maximise weight loss and improve glycaemic control in type 2 diabetes and obesity." (PMID 33933675, 2021). "Dulaglutide is an injectable glucagon-like peptide-1 receptor agonist approved for the treatment of adults with type 2 diabetes." (PMID 34987924, 2021). "Glucagon-like peptide-1 receptor agonists (GLP-1 RAs) are considered the standard of care for type 2 diabetes in many countries worldwide." (PMID 34443410, 2021). "Tirzepatide is a novel once-a-week dual glucose-dependent insulinotropic polypeptide and glucagon-like peptide-1 receptor agonist, currently under trial to assess glycemic efficacy and safety in people with type 2 diabetes." (PMID 34681215, 2021). "GLP-1R peptide agonists, such as Liraglutide and Exenatide, are approved for the treatment of type 2 diabetes mellitus." (PMID 33995091, 2021).